TMEM50A (transmembrane protein 50A)
Synonyms: SMP1; IFNRC
Tractability: Antibody: UniProt predicts a signal peptide or a membrane-spanning region; the Human Protein Atlas places it where antibodies can reach. PROTAC: ubiquitination databases record sites on it; its protein half-life has been measured.
Gene: Protein-coding gene on chromosome 1 (25,338,295 to 25,362,362, forward strand). Ensembl gene ENSG00000183726.
Subcellular location: Membrane
Subcellular location (Human Protein Atlas): Plasma membrane; Actin filaments; Cytosol
Gene Ontology:
Molecular function: protein binding
Biological process: late endosome to vacuole transport via multivesicular body sorting pathway
Cellular component: endoplasmic reticulum; cytoplasm; glial cell projection; membrane; neuronal cell body
Genetic constraint (gnomAD): Loss-of-function variants: 8 observed, 19.16 expected, observed/expected ratio (o/e) 0.42, 90% interval 0.24 to 0.75. The upper end of that interval is the gene's LOEUF score, 0.75, which puts it in group 3 of 6, group 1 being the genes least tolerant of losing a copy. Missense variants: 152 observed, 168.32 expected, observed/expected ratio (o/e) 0.9, 90% interval 0.79 to 1.03. Synonymous variants: 52 observed, 53.76 expected, observed/expected ratio (o/e) 0.97, 90% interval 0.77 to 1.22.
Homologues: Orthologues: macaque TMEM50A (99% identical), dog TMEM50A (97% identical), pig TMEM50A (96% identical), guinea pig TMEM50A (96% identical), mouse Tmem50a (94% identical), rat Tmem50a (92% identical), tropical clawed frog tmem50a (87% identical), zebrafish tmem50a (87% identical), Caenorhabditis elegans Y74C10AL.2 (43% identical), Drosophila melanogaster CG15012 (38% identical). Paralogues in human: TMEM50B (69% identical).
Diseases named in the same sentence as TMEM50A in open-access papers:
TMEM50A is named in the same sentence as 3 diseases in open-access papers, as found by Europe PMC text mining. Sharing a sentence is not in itself a finding about the gene and the disease. The quoted sentences say what the papers report.
cervical cancer (1 paper, 2016). A primary or metastatic malignant neoplasm involving the cervix. "According to the Gene Expression Omnibus (GEO), TMEM50A appears to be highly upregulated in late stage cervical cancer in comparison to normal cells." (PMID 27030248, 2016).
TMEM50A also shares sentences with these, for which no sentence is quoted: cardiac disease (1 paper); heart failure (1).